GPX4 (glutathione peroxidase 4)
Diseases named in the same sentence as GPX4 in open-access papers (continued):
Sharing a sentence is not in itself a finding about the gene and the disease.
gastric cancer (continued). "Previous studies have established that Stat3 interacts with the promoters of GPX4, SLC7A11, and FTH1, thereby modulating their expression levels in gastric cancer, which leads to the formation of a Stat3-ferroptosis regulatory axis." (PMID 41341590, 2025). "Mechanistically, CST1 enhances cellular antioxidant capacity by stabilizing GPX4 protein while promoting EMT, thereby potentiating peritoneal, pulmonary, and hepatic metastasis of gastric cancer cells." (PMID 40919133, 2025). "Then, both HGC27 and HGC27/L cells were treated with different concentrations of baicalin for 24 h to explore the changes of key genes of ferroptosis, such as TfR, FTH1, GPX4 and IREB2 in gastric cancer cells exposed to baicalin with different concentrations." (PMID 38730240, 2024). "OP-B has been observed to significantly degrade glutathione peroxidase 4 (GPX4) and solute carrier family seven member 11 (SLC7A11) following treatment of gastric cancer cells in vitro." (PMID 38738174, 2024). "Ursolic acid and oleanolic acid in ACP, as well as JDA from Jiyuan Rabdosia rubescens, promote ferroptosis in gastric cancer cells by suppressing SLC7A11 and GPX4 expression." (PMID 38292937, 2024). "Herein, we performed immunohistochemistry for GPX4, FSP1, and 4-HNE using tissues from patients with gastric cancer and investigated the relationship between these factors and prognosis." (PMID 39273151, 2024). "In gastric cancer, the beta-catenin/TCF4 transcription complex promotes GPX4 expression and inhibits ferroptosis." (PMID 38778030, 2024). "Meanwhile, the suppression of GPX4 and xCT by TFP was obviously rescued by overexpressing NRF2 in gastric cancer cells." (PMID 38244583, 2024). "However, the role of GPX4-ferroptosis in gastric cancer metastasis remains unclear." (PMID 36369321, 2023). "To explore the effect of CST1 on the ubiquitination of endogenous GPX4 in gastric cancer cells, we used the CST1 knockdown stable cell line MKN45-shNC/MKN45-sh1-CST1/MKN45-sh2-CST1, immunoprecipitated GPX4, respectively, and then detected the Ub level by WB." (PMID 36369321, 2023). "In vivo and in vitro experiments showed that inhibiting GPX4 expression in tumor cells can significantly enhance the infiltration and activation level of CD8+ T cells and improve the prognosis of gastric cancer." (PMID 37649598, 2023). "In gastric cancer, inhibiting CDO1 expression led to the restoration of glutathione levels, increased expression of GPX4, prevented ROS production, and reduced the production of malondialdehyde, which is a final product of lipid peroxidation." (PMID 37740473, 2023). "We demonstrated that CST1 relieves the ubiquitination of GPX4 through OTUB1, thereby promoting ferroptosis resistance in gastric cancer cells." (PMID 36369321, 2023). "To explore the effect of GPX4 inhibitors on gastric cancer tumors with a low HDS, we used five types of gastric cancer cells (HGC27, MKN45, KATOAIII, SNU1, and AGS) stored in the laboratory." (PMID 37649598, 2023). "The expression of GPX4 was higher in CRC, gastric cancer, lymphoma and melanoma, and lower in sarcoma." (PMID 34722530, 2021). "In gastric cancer patients, STAT3 can bind to the consensus DNA response elements within the promoters of NR-related genes (GPX4, SLC7A11, and FTH1) and promote the expression of these ferroptosis-negative regulators, thereby establishing a negative STAT3–ferroptosis regulatory axis (Bottom left)." (PMID 41513612, 2026). "More importantly, quantitative analysis revealed a significant positive correlation between OTUD5 and GPX4 protein levels and advanced stages of gastric cancer, while the p21 protein levels showed a negative correlation with advanced stages." (PMID 40070026, 2025).
gastric cancer (continued). "In the regulation of ferroptosis, STAT3 binds to consensus DNA response elements in the promoters of the genes associated with negative ferroptosis regulation, including GPX4 and SLC7A11 and leads to 5‐FU resistance in gastric cancer." (PMID 40919131, 2025). "Comparing the expression of key proteins involved in ferroptosis in different cells, GPX4 and downstream SLC7A11 may be valuable evaluation indicators for gastric cancer cells (Hgc27 and MKN45)." (PMID 39991579, 2025). "For example, inhibition of STAT3 could regulate GPX4, SLC7A11 and FTHI to induce ferroptosis, which can restore the sensitivity of gastric cancer cells to chemotherapy drugs." (PMID 38347435, 2024). "Our experimental results showed that EM combined with DDP significantly increased the levels of LPO, ROS, and divalent iron ions in MKN45/DDP cells while decreasing the levels of GPX4 and FTH1 proteins in the subcutaneous tumor-resistant nude mouse model of gastric cancer." (PMID 38345573, 2024). "Our results showed that knockdown of TRF2 in gastric cancer cells resulted in the downregulation of SLC7A11 and GPX4 expressions at the mRNA and protein levels, while the expression of SLC7A11 and GPX4 recovered after pretreatment with the ferroptosis inhibitor ferrostatin-1." (PMID 37113742, 2023). "CST1 relieves GPX4 ubiquitination modification by recruiting OTUB1, improving GPX4 protein stability and reducing intracellular reactive oxygen species (ROS), thereby inhibiting ferroptosis and, in turn, promoting gastric cancer metastasis." (PMID 36369321, 2023). "In summary, we confirmed that GPx4 may be a potential target for GC treatment, PB may be a novel and promising drug for the treatment of GC, which shows good antitumor efficacy without causing significant host toxicity via inducing ferroptosis in both gastric cancer cells and mouse models." (PMID 36923926, 2023). "Additionally, propofol was found to decrease GPX4 and SLC7A11 protein levels by suppressing STAT3 expression, decelerating gastric cancer growth in vivo." (PMID 38111578, 2023). "In gastric cancer, STAT3 regulates ferroptosis primarily through its own histone acetylation, which increases its gene-level expression and promotes the expression of downstream direct targets GPX4, SLC7A11, and FTH1, thereby exerting an anti-ferroptotic effect." (PMID 41513612, 2026). "Therefore, we speculate that GPX4 and downstream SLC7A11 are important ferroptosis intervention proteins in gastric cancer cells (Hgc27 and MKN45)." (PMID 39991579, 2025). "For example, cysteine protease inhibitor SN (CST1) could regulate the protein stability of glutathione peroxidase 4 (GPX4) through OTUB1 and inhibit the ferroptosis of gastric cancer cells, which in turn promoted the metastasis of gastric cancer to the liver, lungs and peritoneum." (PMID 40178680, 2025). "STAT3 knockdown in gastric cancer cells provoked a significant inhibition of GPX4, SLC7A11, and FTH1 at both the mRNA and protein levels, and also increased lipid peroxidation and ROS, and enhanced intracellular Fe2+, thus reducing the GSH/GSSG ratio in gastric cancer cells." (PMID 38539832, 2024). "Also, the positive correlation between CST1 and GPX4 expression levels remained unchanged regardless of the degree of gastric cancer tissue differentiation." (PMID 36369321, 2023). "Mechanistically, CST1 relieves GPX4 ubiquitination by recruiting the deubiquitinating enzyme OTUB1, improving GPX4 protein stability and reducing intracellular reactive oxygen species ROS, thereby inhibiting ferroptosis and, in turn, promoting EMT and metastasis of gastric cancer cells." (PMID 36369321, 2023).
gastric cancer (continued). "Moreover, ebselen increased the expression of GPX2 and GPX4 in SGNs after peroxynitrite injury, which is consistent with previous studies that ebselen can increase the expression of GPX2 or GPX4 in rat stomach, gastric cancer cells, or cochlea." (PMID 35401119, 2022). "The WB results of ferroptosis key protein showed that compared with GES1 and MC, there were no significant changes in FSP1 and DHODH in gastric cancer cells (Hgc27 and MKN45), slight changes in GPX4, no significant changes in SLC7A11." (PMID 39991579, 2025). "WB results showed that compared with the blank group added with RSL3, the M2c co culture group added with RSL3 gastric cancer cells (Hgc27 and MKN45) showed no significant decrease in GPX4 protein and downstream SLC7A11 protein." (PMID 39991579, 2025). "In gastric cancer, STAT3 directly bound to the promoters of negative ferroptosis regulators (GPX4, SLC7A11, and FTH1) and modulated their expression." (PMID 38341410, 2024). "Notably, OTUD5 overexpression, knockdown or knockout did not impact the mRNA levels of GPX4, indicating that OTUD5 upregulates GPX4 expression independently of transcriptional level in gastric cancer cells." (PMID 40070026, 2025).
glioma (95 papers, 2017 to 2026). A benign or malignant brain and spinal cord tumor that arises from glial cells (astrocytes, oligodendrocytes, ependymal cells). "An increased methylation level of GPX4 was associated with improved OS in glioma, PAAD, and SKCM, but with poorer OS in HNSC and KIRC." (PMID 41142608, 2025). "Beyond that, SLC1A5, which participates in immune modulation, is positively correlated with GPX4, though the underlying mechanism is ill-defined, suggesting a potential interaction between glioma immune microenvironment and GPX4127." (PMID 39309434, 2024). "The roles of GPX4-independent mechanisms in governing ferroptosis susceptibility of various glioma cell states need further investigation." (PMID 39192032, 2024). "Herein, we demonstrate that murine and human glioma cells are susceptible to ferroptosis via GPX4 inhibition by drugs such as RSL3." (PMID 36864031, 2023). "Collectively, these findings define the role of GPX4 K63-linked polyubiquitination in ferroptosis and suggest a potential strategy for glioma treatment." (PMID 37872147, 2023). "In previous studies, GPX4 was shown to be highly expressed in gliomas and to be closely associated with their progression." (PMID 37375197, 2023). "Recent studies have confirmed that GPX4 activity is associated with chronic inflammation, and current studies have confirmed that glioma progression is related to chronic inflammation." (PMID 35832539, 2022). "Dysregulation of GPX4 has been implicated in several types of cancer, including glioma." (PMID 38020609, 2023). "Subsequently, it was found that DHA induces ferroptosis in glioma cells through the PERK-ATF4-HSPA5-GPX4 pathway, with GPX4 identified as a key target of DHA-mediated ferroptosis in glioblastoma." (PMID 40994946, 2025). "Regarding cancers, it is reported that GPX4 is involved in the proliferation, migration, and apoptosis of glioma cells." (PMID 39858464, 2025). "Elevated β-catenin transcriptionally upregulates TP63, which in turn promotes GPX4 expression and suppresses lipid peroxidation and ROS accumulation, thereby facilitating glioma cell survival and resistance to ferroptotic cell death." (PMID 40796737, 2025). "Additional studies have demonstrated that the ATF4-induced expression of HSPA5, also known as BiP, can prevent GPX4 degradation and protect against ferroptosis in pancreatic ductal adenocarcinoma and glioma cells." (PMID 40227255, 2025). "The gene mutation of GPX4 did occur in certain cancers, such as SARC, ACC, Glioma, miscellaneous neuroepithelial tumors, and CHOL, OV and CESC, but the proportion of such gene mutations was no more than 8%." (PMID 41142608, 2025). "“GPX4” and “reactive oxygen species” are critical sites of action and manifestations of ferroptosis in glioma." (PMID 40822852, 2025). "GPX4 mRNA expression was substantially associated with the prognosis of COAD, Glioma, Liver hepatocellular carcinoma, and other cancers, as determined using the Sangerbox database." (PMID 40746894, 2025). "The upregulation of HSPA5 increases the expression and activity of GPX4, while GPX4 protects glioma cells from ferroptosis by neutralizing DHA-induced LPO." (PMID 39940964, 2025). "Recent findings suggest that 29 restrains glioma development by targeting NQO1/GPX4-mediated ferroptosis, positioning it as a prospective ferroptosis inducer or glioma therapy." (PMID 40076568, 2025). "Western blot results on tumor tissues demonstrated that PAX6 overexpression can reduce the expression of the GPX4 protein in glioma cells, indicating the potential role of PAX6 in inducing ferroptosis in glioma cells." (PMID 41154694, 2025).
glioma (continued). "Conversely, NF-κB pathway activation in GPX4 knocked-down glioma cells decreased ATF4 and SLC7A11 expression and significantly increased the occurrence of ferroptosis." (PMID 38539832, 2024). "In summary, our findings collectively demonstrate that IGF2BP3 plays a pivotal role in modulating GPX4 by directly interacting with GPX4 mRNA, thereby orchestrating the regulation of ferroptosis in glioma." (PMID 38429265, 2024). "A previous study showed that shikonin can induce iron death in glioma cells by inhibiting xCT and GPX4 expression." (PMID 39703392, 2024). "Lastly, the anti-cancer drug apatinib restrains gliomas partially through decreasing GPX4 and amplifying ferroptosis." (PMID 39309434, 2024). "In turn, this altered metabolic phenotype led to high dependency on GPX4 activity in astrocyte-like glioma populations." (PMID 39192032, 2024). "Glioma cells show a high expression level of GPX4, which leads to tumor progression and chemoresistance." (PMID 39062119, 2024). "Overall, these findings support a cell state-specific metabolic vulnerability to GPX4 inhibition and ferroptosis in quiescent AC-like glioma cell populations." (PMID 39192032, 2024). "Treatment of patient-derived early-passage cell lines and glioma slice cultures generated from surgical samples with a GPX4 inhibitor induced selective depletion of quiescent astrocyte-like glioma cell populations with similar metabolic profiles." (PMID 39192032, 2024). "Simultaneously, Salmonella YB1 was reported to decrease glutathione peroxidase-4 expression, induce mitochondrial atrophy, and increase malondialdehyde and ROS production in glioma cells, leading to iron death in glioma cells." (PMID 38930435, 2024). "Par-4-mediated lipid peroxidation parallels the sensitivity of glioma cells to FINs based on levels of ferroptosis markers, such as GPX4 degradation, labile iron overload, ROS generation, and cell death." (PMID 38886572, 2024). "It has become a consensus that there exists GPX4-independent anti-ferroptosis axis in cells, which has garnered attention in terms of synergizing with classical ferroptosis inducers in treating gliomas." (PMID 39309434, 2024). "There is mounting evidence supporting the strategy of targeting GPX4 to induce iron‐dependent cell death as a promising approach to treat gliomas." (PMID 38685674, 2024). "Recent research has shown quiescent, astrocyte-like glioma cell populations have a unique metabolic vulnerability to GPX4 inhibition, which induces ferroptosis." (PMID 39204078, 2024). "To assess the role of CIRBP in ferroptosis, we analyzed its effect on erastin-induced and ferrostatin 1-inhibited ferroptosis in glioma cells and expression of GPX4 and SLC7A11, which are markers of ferroptosis." (PMID 39857625, 2024). "While our study has advanced our understanding of the intricate interplay between IGF2BP3, GPX4, and ferroptosis regulation in glioma, it has also surfaced intriguing questions that warrant further exploration." (PMID 38429265, 2024). "Some natural extracts drastically trigger glioma ferroptosis and progression arrest by impacting on GPX4." (PMID 39309434, 2024). "Targeting NQO1/GPX4-mediated ferroptosis by plumbagin suppresses in vitro and in vivo glioma growth." (PMID 39193375, 2024). "Overall, these findings demonstrate the significant limitations of cell culture models in studying cell state-specific sensitivity to GPX4 inhibition in glioma." (PMID 39192032, 2024). "For instance, it has been discovered to promote ferroptosis in NSCLC by modulating SLC7A11/GPX4, and it can induce ferroptosis in glioma cells by the ACSL4/GPX4 pathway, thus providing antitumor benefits." (PMID 39266965, 2024). "Taken together, these data indicate that TRIM26 promotes tumorigenesis of glioma by suppressing ferroptosis via GPX4." (PMID 37872147, 2023). "Based on a Western blot analysis, enhanced transfection with a JUN plasmid increases GPX4 protein expression in glioma cells." (PMID 37375197, 2023).